EGFR (epidermal growth factor receptor)
Diseases named in the same sentence as EGFR in open-access papers (continued):
Sharing a sentence is not in itself a finding about the gene and the disease.
Insulin resistance (59 papers, 2012 to 2025). Increased resistance towards insulin, that is, diminished effectiveness of insulin in reducing blood glucose levels. "Liver specific ablation of Mig-6 also causes hyperglycemia and insulin resistance in mice by increasing phosphorylation of insulin receptor substrate 1 (IRS-1) at serine 307 via EGFR-dependent manner." (PMID 39937764, 2025). "Selective loss of EGFR in adipose tissue macrophages inhibits their proliferation and monocyte infiltration into adipose tissue, thereby reducing obesity and insulin resistance." (PMID 41459526, 2025). "The functions of IGF2BP2 are associated with insulin resistance, and insulin regulates the EGFR gene to promote the migration of human corneal epithelial cells." (PMID 37998047, 2023). "Excess FGL1 also causes obesity-related insulin resistance in skeletal muscle through the EGFR/JNK mediated pathway." (PMID 34975333, 2022). "In a recent clinical study in a Japanese population with type 2 diabetes, soluble EGFR as a hepatokine was indicated to be associated with insulin resistance in the liver." (PMID 35956419, 2022). "The correlation of soluble EGFR with hyperlipidemia and fasting hyperglycemia is associated with the correlation between soluble EGFR and hepatic insulin resistance." (PMID 33005239, 2020). "Soluble EGFR, a hepatokine, is correlated with insulin resistance in the liver, while adipsin, an adipokine, is associated with adipose insulin resistance." (PMID 33005239, 2020). "EGFR signaling is associated with insulin resistance and inflammation in the liver, muscle, and adipose tissue." (PMID 31815004, 2019). "Moreover, insulin resistance and diabetic nephropathy (DN) in T2D are associated with epidermal growth factor receptor (EGFR) activation." (PMID 38916734, 2024). "The stimulation of the EGFR signaling pathway is strongly linked to obesity and insulin resistance." (PMID 37835227, 2023). "However, poor metabolic health is associated with insulin resistance and consequently activation of insulin-like growth factor-I and epidermal growth factor receptor (EGFR)." (PMID 35062912, 2022). "Whether elevated C6, C8 and EGFR are the cause or consequence of insulin resistance still needs to be determined." (PMID 35964946, 2022). "In addition, inhibition of EGFR activation is associated with improved DN and insulin resistance in type 2 diabetes mouse models." (PMID 33628839, 2021). "Furthermore, one recent study has indicated that inhibition of EGFR by erlotinib is associated with improved diabetic nephropathy and insulin resistance in animal model with type 2 diabetes." (PMID 32663210, 2020). "EGFR signaling is associated with insulin resistance and liver, muscle, and adipose inflammation." (PMID 31676778, 2019). "The fifth factor in our research focuses on EGFR activity, which directly contributes to insulin resistance and diabetic nephropathy." (PMID 38916734, 2024). "With molecular mechanisms involved in the impact of macrophages on insulin resistance, a high-fat diet increased the expression of epidermal growth factor receptor (EGFR) and its ligand amphiregulin in ATM." (PMID 37274349, 2023). "In summary, these results demonstrate that EGFR expression and activation in myeloid-derived cells plays an important detrimental role in the development of insulin resistance in obesity." (PMID 35948530, 2022). "Here, the authors show that selective deletion of the epidermal growth factor receptor in ATMs decreased obesity and development of insulin resistance." (PMID 35948530, 2022). "We showed significant correlations between the serum soluble EGFR level and liver insulin resistance and between the serum adipsin level and fat insulin resistance in this study." (PMID 33005239, 2020). "Here, we investigated the significance of soluble EGFR and adipsin as biomarkers for insulin resistance in Japanese subjects with type 2 diabetes." (PMID 33005239, 2020).
Insulin resistance (continued). "The inhibition of VEGFR2 or EGFR are believed to be other hypoglycaemic mechanisms in this group of compounds, which reduce inflammation of the pancreas and insulin resistance." (PMID 32016844, 2020). "To investigate the significance of soluble EGFR and adipsin as biomarkers for insulin resistance in Japanese subjects with T2DM, we measured the serum levels of EGFR and adipsin." (PMID 33005239, 2020). "When these parameters were categorized according to the correlation with soluble EGFR or adipsin, distinctive features of insulin resistance emerged." (PMID 33005239, 2020). "When gefitinib, an EGFR tyrosine kinase inhibitor, was treated in high-fat diet fed Mig-6d/d mice, fasting insulin concentration, insulin resistance, and hypercholesterolemia were ameliorated." (PMID 28053990, 2016). "Recently it was demonstrated that mTOR participates in EGFR signaling in beta cells during glucose and intralipid infusion induced insulin resistance, where the compensatory beta cell mass expansion was stimulated via the EGFR-PI3K-mTOR pathway." (PMID 24695557, 2014). "This serotoninergic synergy between IRS-1 phosphorylation and HB-EGF-mediated EGFR stimulation has been demonstrated to play a key role in serotonin-induced insulin resistance." (PMID 22754566, 2012). "CEACAM1 therefore appears to play a central role in connecting EGFR activity with the control of central obesity/insulin resistance." (PMID 22754566, 2012). "In liver-specific Mig-6 ablation mice, insulin resistance increased in an EGFR-dependent manner." (PMID 39937764, 2025). "SGLT1 may contribute to cardiac injury in obesity and insulin resistance by stimulating ROS through its interaction with EGFR." (PMID 40932483, 2025). "The inhibition of EGFR reduced the development of obesity and insulin resistance." (PMID 37274349, 2023). "Similarly, increased level of circulating soluble EGFR have been shown to positively correlate with hepatic insulin resistance in both obese mice and people with type 2 diabetes." (PMID 35964946, 2022). "These negative results indicated that the protection against insulin resistance seen in Waved 2 mice in response to the HFD was not due to deficient EGFR activity in the primary peripheral insulin sensitive cell tissues." (PMID 35948530, 2022). "Because insulin resistance is closely associated with NAFLD, reducing cytokine levels and M1 macrophage infiltration may be additive mechanisms through which EGFR inhibition improves NAFLD." (PMID 30735525, 2019). "Similarly, we observed that SOS2 was another seeder gene that was linked with SRC, INSRR, EGFR, FGFR1, PGFRA and PGFRB gene signatures that were significantly associated with insulin resistance and type 2 diabetes." (PMID 28179884, 2017). "In summary, our study showed that ablation of Mig-6 in the liver results in multiple metabolic phenotypes, and that treatment with an EGFR tyrosine kinase inhibitor improved hypercholesterolemia and insulin resistance, suggesting a possible role for EGFR signaling in cholesterol metabolism." (PMID 25486251, 2014). "Notably, our analysis revealed crucial hub targets such as EGFR, SRC, ESR1, MAPK1, and CASP3, alongside implicated signaling pathways, including those related to insulin resistance, the FoxO signaling pathway, the PPAR signaling pathway, and the IL-17 signaling pathway." (PMID 38845779, 2024). "An integrated system pharmacology analysis then revealed that various targets such as PPARG, RELA, EGFR and numerous pathways such as TNF signalling, PI3K-Akt signalling, MAPK signalling and NF-κB signalling were involved in the underlying mechanisms of GQD in improving diabetic insulin resistance." (PMID 36187136, 2022). "Furthermore, remarkable obesity, a cause of insulin resistance, is rare among both T2DM patients and NGT subjects in the Japanese population; this may obscure differences in the serum soluble EGFR and adipsin levels between these two groups." (PMID 33005239, 2020).
Insulin resistance (continued). "However, the involvement of serum soluble EGFR and adipsin in insulin resistance remains unclear in the context of pathological conditions." (PMID 33005239, 2020). "Additionally, the effects of high-fat diet were revealed to be more significant in the Mig-6d/d mice, especially in plasma cholesterol profiles in spite of improved insulin resistance, suggesting an important role EGFR signaling pathway in the liver lipid metabolism and insulin resistance." (PMID 28053990, 2016). "Moreover, gefitinib treatment in high-fat diet Mig-6d/d mice showed decreases in fasting insulin concentration and insulin resistance, suggesting gefitinib may improve metabolic syndrome in those with dysregulated EGFR and/or its signaling pathway." (PMID 25486251, 2014). "Conversely, EGFR and FGF8 were no longer significant indicating that these are dependent on IR, in accord with the literature for EGFR, while FGF8 modulation by insulin resistance is a novel finding." (PMID 40072105, 2025). "In contrast, both EGFR and its ligand, amphiregulin, markedly increased in ATMs in HFD-induced obesity, and selective deletion of EGFR in ATMs reduced HFD-induced obesity, adipose tissue derangements and insulin resistance." (PMID 35948530, 2022). "Selective deletion of EGFR in ATMs inhibited both resident ATM proliferation and monocyte infiltration into adipose tissue and decreased obesity and development of insulin resistance." (PMID 35948530, 2022). "Circulating soluble epidermal growth factor receptor (soluble EGFR) and adipsin levels are altered in obese diabetic mice and are possibly correlated with insulin resistance in both mice and humans." (PMID 33005239, 2020). "In addition to this functional system bridge between neuronal and metabolic systems, ligands of Gαq/11-coupled GPCRs that are associated with insulin resistance, such as serotonin, endothelin-1, and thrombin, may also stimulate HB-EGF production and transactivate EGFR in 3T3-L1 adipocytes." (PMID 22754566, 2012). "From KEGG enrichment analysis, the AGE-RAGE, PI3K-Akt, IL-17, MAPK, TNF, EGFR, HIF-1, Apoptosis, Toll-like receptor, Insulin resistance, VEGF, Rap1, NF-kappa B, JAK-STAT, PPAR and Wnt pathway were displayed as the critical signaling participated in the role of QDDHG on DKD." (PMID 37954274, 2023). "Cordyceps may play a crucial role in the treatment of DN by targeting TNF, MAPK1, EGFR, ACE, and CASP3 signaling and involved in the inflammatory response, apoptosis, oxidative stress, and insulin resistance." (PMID 33628839, 2021). "Correspondingly, EGFR inhibition could substantially improve insulin sensitivity by reducing inflammation in insulin target tissue in obese mice, where EGFR inhibition enhances IRS-1 signaling, providing a potential therapeutic target for insulin resistance." (PMID 31815004, 2019). "To investigate whether EGFR in hepatocytes mediated insulin resistance resulting from the HFD, we generated mice with selective EGFR deletion in hepatocytes (Alb1-Cre; EGFRf/f, hepatocyte EGFR−/−) and corresponding WT (EGFRf/f) mice and fed them the HFD for 12 weeks." (PMID 35948530, 2022). "However, selective deletion of EGFR in peripheral insulin-sensitive tissues, hepatocytes, skeletal muscle or adipocytes, failed to alter the onset of obesity and the insulin resistance." (PMID 35948530, 2022). "Our previous findings showed that adipsin, an adipokine, might be correlated with fat insulin resistance in a manner that is independent of the aspect of insulin resistance that is correlated with soluble EGFR." (PMID 33005239, 2020). "However, despite this relatively improved benefit of combining MK2206 and gefitinib in EGFR M+ cells, preclinical data using mouse models has shown that combined inhibition of both AKT1 and AKT2 can result in insulin resistance as well as hyperglycaemia and hyperinsulinaemia." (PMID 24946858, 2014).
psoriasis (59 papers, 2009 to 2025). An autoimmune condition characterized by red, well-delineated plaques with silvery scales that are usually on the extensor surfaces and scalp. "Here, upregulation of EGFR is associated with psoriasis, via regulation and interaction with other factors, as Decoy receptor 3 (DcR3)." (PMID 39966897, 2025). "Growth factors and their receptors such as VEGFA, EGF, and EGFR were also inextricably linked with psoriasis." (PMID 35265149, 2022). "Activation of EGFR/AKT/ERK pathway has been reported as implicated in the pathogenesis of psoriasis and influencing differentiation, proliferation and apoptosis-related genes expression." (PMID 30613363, 2018). "EGFR and its related receptors are well known markers in several solid tumors and their expression and signaling are implicated in psoriasis pathogenesis as well." (PMID 23189171, 2012). "Overexpression of miR-215-5p inhibited the proliferation of human keratinocytes (HaCaTs) cell and diminished psoriasis-like inflammation through DYRK1A-mediated regulation of the EGFR signaling pathway." (PMID 40861221, 2025). "Network pharmacology analysis showed that 20 transdermal constituents were associated with potential therapeutic targets for psoriasis, including TNF, MMP9, TLR4, ICAM1, EGFR, and MAPK14." (PMID 41012530, 2025). "Collectively, these mechanistic, cellular, and structural features support Myr as a rational lead for EGFR-related multi-target modulation in psoriasis." (PMID 41471291, 2025). "Among the key signaling pathways involved in psoriasis, the epidermal growth factor receptor (EGFR) and the PI3K-AKT pathway have been identified as critical regulators." (PMID 41471291, 2025). "EGFR also plays a role in wound closure repair and chronic inflammatory disease, such as allergic dermatitis and psoriasis." (PMID 39966897, 2025). "Collectively, this study demonstrates a role for ALOX15B in the resolution of psoriasis through modulation of EGFR and STAT1 via lipid peroxidation." (PMID 39843435, 2025). "Nevertheless, it has been demonstrated that the upregulation of EGFR or its ligand expression plays an important role in the occurrence and development of chronic inflammatory skin disorders such as psoriasis." (PMID 38059627, 2024). "Few experimental animal model studies have discussed the involvement of EGFR in the pathogenesis of atopic dermatitis and psoriasis, in addition to its potential organizing role in epidermis." (PMID 38454571, 2024). "Of note, there are reported cases treated for cancers with EGFR-blockade agents (cetuximab and erlotinib) resulting resolution of concomitant psoriasis." (PMID 38312837, 2024). "Overexpression of EGFR has been detected in psoriasis, and increased levels of multiple EGFR ligands, such as epiregulin, are found in the psoriatic epidermis." (PMID 36232814, 2022). "Previously, we found that DcR3 is upregulated in the serum and lesional skin of patients with psoriasis and is upregulated by EGFR activation in proliferating primary human epidermal keratinocytes." (PMID 35478210, 2022). "Aberrant activation of EGFR leads to overproliferation of keratinocytes, contributing to psoriasis, while EGFR inhibitors switch keratinocytes from a proliferative to a differentiative phenotype, thus affecting epidermal development and barrier function." (PMID 35478210, 2022). "Downregulation of miR-146a in psoriasis promotes keratinocyte proliferation via the activation of a direct target, epidermal growth factor receptor (EGFR)." (PMID 32806619, 2020). "As described in connection with psoriasis, the role of miR-146a/EGFR axis in keratinocyte proliferation has been reported." (PMID 32806619, 2020). "The role of downregulated miR-146a in SCC has been identified by activating the EGFR target, similar to psoriasis." (PMID 32806619, 2020).
psoriasis (continued). "In chronic inflammatory skin disorders such as psoriasis, there is an upregulation of EGFR and expression of its ligands, whereas in fibrotic skin scarring, enhanced TGF-β expression has been observed." (PMID 32283613, 2020). "For example, EGFR and its ligands are overexpressed in patients with psoriasis, and increased serum EGF concentrations correlate with the severity of psoriasis." (PMID 33096942, 2020). "Consistent with the present results, it has been demonstrated that the inhibition of EGFR by erlotinib or cetuximab successfully improves severe psoriasis." (PMID 31936670, 2020). "Indirubin plays a crucial role in inhibiting the occurrence and development of psoriasis by inhibiting the activity of EGFR (Epidermal growth factor receptor)." (PMID 32795328, 2020). "Several skin disorders including psoriasis are related to the anomalous activation of EGFR signaling." (PMID 32283613, 2020). "Consistent with these notions, the inhibition of EGFR by erlotinib or cetuximab successfully improves severe psoriasis." (PMID 32070069, 2020). "Our study underscores the potential role of new therapies such as anti-CCL20 antibody and EGFR/ERK inhibitors in the management of psoriasis." (PMID 31936670, 2020). "Based on the fact that the EGFR signaling pathway plays an important role in the development of psoriasis, here we reported the pharmacokinetics, safety, and preliminary efficacy of icotinib cream in Chinese psoriasis patients." (PMID 31187048, 2019). "In conclusion, TWEAK/Fn14 signals contribute to the development of psoriasis, and involves the modulation of resident cells and the transduction of the EGFR pathway." (PMID 30038329, 2018). "Epidermal growth factor receptor is a gene overexpressed in psoriasis that can promote the proliferation of keratinocytes 6,8, thus contributing to the development of psoriasis." (PMID 25209759, 2014). "EGFR signaling participates in psoriasis through its promotion of keratinocyte proliferation, and production of growth factors such as VEGF." (PMID 25384035, 2014). "EGFR stimulation leads to keratinocyte proliferation, and contributes to epidermal hyperplasia in psoriasis and the skin phenotypes of K5.Stat3C mice as well." (PMID 25384035, 2014). "Vitamin D helps in reducing the proliferation of keratinocytes, hence treating psoriasis by inhibiting the growth cycle of the TGF-α/EGFR (epidermal growth factor receptor)." (PMID 24967240, 2013). "In addition to its well-known anti-inflammatory properties, this study revealed that Myr exerts therapeutic effects on psoriasis by modulating the activity of EGFR, a pivotal receptor tyrosine kinase regulating epidermal homeostasis." (PMID 41471291, 2025). "IQGAP3 knockdown inhibited EGFR signaling, which plays a crucial role in epidermal homeostasis and regulation of skin inflammatory responses and has elevated expression in active epidermal lesions of psoriasis." (PMID 38674130, 2024). "However, the upregulation of EGFR was involved in the development of several dermatologic diseases, including psoriasis." (PMID 38059627, 2024). "In psoriasis, maintenance of EGFR activity can be observed in the upper epidermal layer." (PMID 35478210, 2022). "Dysregulation of the EGFR-DcR3 axis leads to impaired keratinocyte differentiation in psoriasis." (PMID 35478210, 2022). "Extensive data reported the role of two variants, namely, rs712829 residing in EGFR gene and rs1143627 in IL1B gene in NCI-60 cancer cell lines and human samples, highlighting the effect of genotype on neoplasms and psoriasis on the usage of diverse drugs molecules." (PMID 36164436, 2022). "Since EGFR activation is instrumental in psoriasis, we examined whether EGFR activation regulates PKM2 expression in the keratinocyte." (PMID 34733164, 2021). "As both epidermal growth factor receptor (EGFR) activation and ERK1/2 signal pathway are instrumental in psoriasis, we examined whether EGFR and ERK1/2 activation regulate PKM2 functions in keratinocytes." (PMID 34733164, 2021).